IFNAR1 (interferon alpha and beta receptor subunit 1)
Diseases named in the same sentence as IFNAR1 in open-access papers (continued):
Sharing a sentence is not in itself a finding about the gene and the disease.
malaria (continued). "We used this experimental setting to analyze inflammatory mediators known to be involved in the host response to malaria parasites, namely, Toll-like receptor 4 (TLR4) and type I interferon receptor 1 (IFNAR1)." (PMID 29440369, 2018). "Here, using two mouse models of non-lethal blood-stage malaria, we have provided evidence that the onset of protective humoral immunity to Plasmodium can be influenced by an innate cytokine signalling pathway, in this case Type I Interferon-signalling via IFNAR1." (PMID 27812214, 2016). "Here, we explored the effect of Type I Interferon signalling via IFNAR1 on CD4+ T-cell and B-cell responses in two non-lethal murine models of malaria, P. chabaudi chabaudi AS (PcAS) and P. yoelii 17XNL (Py17XNL) infection." (PMID 27812214, 2016).
diabetes (14 papers, 2011 to 2024). "In keeping with those findings we show that IFNAR1 deficient 8.3 mice also have normal diabetes incidence and CD8+ T cells have normal levels of granzyme B expression after transfer and isolation from NOD islets." (PMID 31653894, 2019). "After mock inoculation, the overall diabetes incidence was higher in NOD.IFNAR1−/− mice than NOD mice (p = 0.0003)." (PMID 27405244, 2016). "Mock- and RRV-infected female NOD and NOD.IFNAR1−/− mice were bred, inoculated and monitored concurrently for diabetes onset under identical environmental conditions." (PMID 27405244, 2016). "EVA1C is a Slit receptor involved in Robo-mediated axonal guidance, OLIG2 regulates spinal cord oligodendrocyte and motor neuron development, IFNAR1 is an interferon receptor with no role in the initiation or progression of diabetes and RUNX1 is involved in haematopoiesis." (PMID 27195491, 2016). "Incidence in NOD and NOD.IFNAR1−/− was indistinguishable, however short-course administration of an IFNAR1 blocking antibody to NOD animals 15–25 postpartum significantly delayed the onset of diabetes." (PMID 28959234, 2017). "Notably, diabetes rates were indistinguishable between mock- and RRV-inoculated NOD.IFNAR1−/− mice (p > 0.05)." (PMID 27405244, 2016). "However, RRV-infected NOD.IFNAR1−/− mice exhibited delayed pDC and lymphocyte activation, no T helper 1 bias in RRV-specific antibodies and unaltered diabetes onset when compared with uninfected controls." (PMID 27405244, 2016).
encephalitis (14 papers, 2008 to 2025). An acute inflammatory process affecting the brain parenchyma. "Encephalitis post-MMR, associated with detection of vMeV in CSF, has been reported in homozygous IFNAR1 [27••] deficiency." (PMID 34107321, 2021). "Herpes simplex virus 1 (HSV-1) encephalitis (HSE) has been reported in a patient with a distinctive form of AR complete IFNAR1 deficiency in which a non-functional IFNAR1 is expressed on the cell surface at levels similar to those typically observed for the wildtype IFNAR1." (PMID 39680367, 2025). "However, a defective IFN-I response enhanced virus replication, accelerated lethality, and shifted the inflammatory response from a monocyte/macrophage-dominated encephalitis that is independent of adaptive immune cells in WT mice to a neutrophil-dominated encephalitis in Ifnar1−/− mice." (PMID 31511023, 2019). "Life-threatening illness including encephalitis, in temporal association with MMR administration, has also been reported in homozygous deficiency of STAT1, STAT2 and IFNAR1, although vaccine origin could not be definitely proven [28, 29, 30,31••]." (PMID 34107321, 2021).
pneumonia (14 papers, 2017 to 2025). An acute, acute and chronic, or chronic inflammation focally or diffusely affecting the lung parenchyma, caused by an infection in one or both of the lungs (by bacteria, viruses, fungi, or mycoplasma.). "The importance of type I IFN signaling during K. pneumoniae-induced pneumonia was assessed by infecting type I IFN 1 receptor-deficient (Ifnar1-/-) mice." (PMID 29112952, 2017). "Heterozygous variants in POL3RA and IFNAR1 were found in P15 (critical pneumonia)." (PMID 36880831, 2023). "During pneumonia, lung neutrophils upregulated expression of Ifnar1 and Ifnar2 mRNA 2.3 and 1.5 fold, respectively (FDR < 0.05)." (PMID 28900269, 2017). "In hindsight, treatment of SARS-CoV2-induced pneumonia in P1 - even prior to a genetic diagnosis - likely facilitated relatively early recovery and survival given the well-known severity of SARS-CoV2 infection in IFNAR1/IFNAR2-deficient patients." (PMID 39098944, 2024). "This contrasted with interferon alpha and beta receptor subunit 1 (IFNAR1)–deficient cells from patients prone to hypoxemic pneumonia without MIS-C." (PMID 36538032, 2023). "Conversely, and consistent with the lack of pneumonia in patients with MIS-C, a lung epithelial cell line and fibroblasts defective for this pathway restrict SARS-CoV-2 normally, unlike IFNAR1-deficient cells from patients prone to hypoxemic pneumonia without MIS-C." (PMID 41347066, 2025).
Hepatitis (13 papers, 2010 to 2025). Inflammation of the liver. "In contrast to these proposed cell-mediated mechanisms of liver injury, hepatitis in infected Ifnar1-/- mice results from cell-intrinsic innate immune responses to the virus." (PMID 34591933, 2021). "Ifnar1-/- mice recapitulate many of the cardinal features of hepatitis A in humans, including hepatocyte apoptosis and elevated serum ALT levels." (PMID 34591933, 2021). "HAV-infected Ifnar1-/- mice recapitulate many of the cardinal features of hepatitis A in humans, including serum alanine aminotransferase (ALT) elevation, hepatocellular apoptosis, and liver inflammation." (PMID 34591933, 2021). "The practical relevance of the mechanisms utilizing IFNAR1 elimination to attenuate the responsiveness of tissues to IFN in hepatitis is underscored by several clinical observations." (PMID 24480543, 2014). "The importance of IFNAR1 ubiquitination within the central immune compartment for tissue protection was next investigated in the hepatitis model induced by CCl4." (PMID 24480543, 2014). "These alterations in Ifnar1SA mice together with a more pronounced leukocyte infiltration strongly suggest that ubiquitination of IFNAR1 plays a protective role during hepatitis of either autoimmune or toxic etiology." (PMID 24480543, 2014). "Staining of these same tissues with hematoxylin and eosin (H & E) revealed minimal multifocal hepatitis with signs of inflammation at 3 dpi, and moderate diffuse hepatitis with coagulative necrosis and extra medullary granulopoiesis in the liver of Ifnar1-/- mice." (PMID 31194854, 2019). "To ascertain whether HSP90 activity is required for efficient HAV replication in vivo, we utilized a small animal model of hepatitis A, administering 17-AAG to Ifnar1-/- mice 1 day after infection with murine-passaged HM175 virus." (PMID 40470959, 2025). "The absence of liver injury in Mavs-/- mice shows that HAV replication is noncytopathic, and that hepatitis in Ifnar1-/- mice results from the host response to the infection." (PMID 34591933, 2021). "Pharmacologic stimulation of IFNAR1 ubiquitination is protective against from toxic hepatitis and fulminant generalized inflammation in wild type but not Ifnar1SA mice." (PMID 24480543, 2014). "Consistent with the notion that hepatitis results from cell-intrinsic responses, prior depletion of CD4+ or CD8+ T cells, NK/NK-T cells, or phagocytic macrophages has no impact on the development of hepatitis following intravenous challenge of Ifnar1-/- mice with HAV." (PMID 34591933, 2021). "Recent studies have shown, however, that Ifnar1-/- mice lacking expression of the type I interferon (IFN) receptor are highly permissive for infection with hepatitis A virus (HAV), the causative agent of type A hepatitis in humans." (PMID 34591933, 2021). "Indeed, treatment with LPA capable of inducing IFNAR1 ubiquitination protected wild type but not Ifnar1SA animals from toxic hepatitis and fulminant generalized inflammation." (PMID 24480543, 2014).
parasitemia (13 papers, 2012 to 2023). "Together, these results suggest that the maternal IFNAR1 action in MiP pathogenesis favors increased peripheral parasitemia and possibly contributes to fetal weight loss." (PMID 29440369, 2018). "The parasitemia between PbA-infected Ifnar1-/- mice and eosinophil depleted PbA-infected Ifnar1-/- mice was comparable." (PMID 34659202, 2021). "Irf7−/− mice only partially recapitulated the decreased brain pathology and protection from P. berghei (ANKA) lethality observed in Ifnar1−/− mice, but loss of IRF7 perfectly phenocopied the decreased parasitemia observed in Ifnar1−/− mice." (PMID 33408718, 2020). "Ifnar1-/- mice displayed similar initial parasitemias compared to infected WT controls for the first two weeks of infection, but thereafter exhibited faster control of blood-stage parasites than WT controls." (PMID 27812214, 2016). "Additionally, Sebina and colleagues showed that IFNAR1 deletion in P. yoelii (Py17XNL) infection increased pathogen-specific antibody titers and decreased parasitemia late in infection (17–21 dpi)." (PMID 33408718, 2020). "We treated PcAS-infected Ifnar1-/- and WT mice with a moderate dose of α-ICOSL blocking antibody (100μg) and at day 8 p. i. examined antibody production and parasitemia." (PMID 27812214, 2016). "We inoculated mice lacking the type I IFN receptor (Ifnar1-/-) or control WT B6 mice with Py YM, and monitored survival and blood parasitemia." (PMID 27792766, 2016). "In another study, the effect of Ifnar1−/− on P. chabaudi AS parasitemia may not be significant, but the day 6 parasitemia is higher in the Ifnar1−/− than those of WT mice." (PMID 33344264, 2020). "Paradoxically, in the context of experimental Plasmodium infection, the differentiation of TFH cells, GC B cells, and Ab responses are significantly enhanced in Ifnar1−/− mice or upon anti-IFNAR1 Ab neutralization, implying a negative role of IFNα/β signaling in parasitic infections." (PMID 30405612, 2018).
autoimmune disease (11 papers, 2011 to 2024). A disorder resulting from loss of function or tissue destruction of an organ or multiple organs, arising from humoral or cellular immune responses of the individual to their own tissue constituents. "While autoantigens and other autoimmunity components may contribute to AAA disease, the current findings linking IFNAR1 to experimental AAA pathogenesis provide further insights into the positive association between autoimmune diseases and aortic aneurysms." (PMID 36291750, 2022). "This region is important for the interaction of TYK2 with IFNAR1, its function, as well as for maintaining the expression of IFNAR1 on the cell surface, suggesting that this SNP may reduce the function of TYK2 and thus susceptibility to autoimmune diseases." (PMID 23227085, 2012). "Adding to evidence for IFN-I in autoimmune disease, recent phase III trials using an IFNAR1 monoclonal antibody blocking IFN-I activity (Anifrolumab) to treat SLE shows promising disease modifying activity." (PMID 34917078, 2021). "In contrast, B cell-specific IFNAR1 expression accelerated the kinetics but was not required for the generation of autoimmune disease on the same autoimmune background." (PMID 39440973, 2024). "Based on the regulation of the IFNAR1 pathway by TREM2, we hypothesize that TREM2 modulation may serve as a therapeutic modality for autoimmune diseases." (PMID 38956653, 2024). "While investigations into its functional impact are lacking, limited reports suggest that rs2257167 increases IFNAR1 expression, which may positively impact the antiviral immune response during infection, but also increase the propensity to develop autoimmune disease." (PMID 34917078, 2021).
Immunodeficiency (10 papers, 2015 to 2025). Failure of the immune system to protect the body adequately from infection, due to the absence or insufficiency of some component process or substance. "A number of studies have used Ifnar1-/- mice to evaluate the effectiveness of vaccines despite the immunodeficiency of the mice." (PMID 32556415, 2020). "APOH (Apolipoprotein H) and IFNAR1 (Interferon Alpha, Beta, Omega Receptor) are involved in immune disorders." (PMID 25945798, 2015). "However, because of its reliance on a precondition of immunodeficiency (i.e. Ifnar1 knockout mice), more work is necessary to show whether it will accurately reproduce the human condition." (PMID 28231241, 2017).
Obesity (10 papers, 2017 to 2025). Accumulation of substantial excess body fat. "However, IFNAR1 deficiency improves glucose tolerance in diet-induced obesity." (PMID 37830559, 2023). "•The resistance to diet-induced obesity and browning of white adipose tissue was dependent on IFNAR1." (PMID 32180554, 2020). "The overexpression of interferon beta (IFNβ), for instance, may protect adipocytes in obesity and a lack of adipocyte interferon alpha and beta receptor subunit 1 (IFNAR1) worsens the metabolic effects of diet-induced obesity." (PMID 37830559, 2023). "Similarly, monoclonal antibodies targeting IFN-α (sifalimumab) or IFNAR1 (anifrolumab) and specific ablation of pDCs, which are the main IFN-I producing cells, may also have therapeutic value in obese individuals in addition to SLE patients in view of the importance of the pDC-IFN-I axis in obesity." (PMID 33574823, 2020).
Splenomegaly (10 papers, 2016 to 2025). Abnormal increased size of the spleen. "Due to the splenomegaly in Ifnar1-/- mice, we still observed elevated total splenic CD4+ T cell counts in PbA-infected Ifnar1-/- mice in comparison to infected WT mice." (PMID 34659202, 2021). "We also photographed and weighed the spleens of PD-L1 wt and PD-L1−/− mice after primary tumor IR and found that tumor-caused splenomegaly was significantly relieved by IR and HCQ treatment, but this retardation was partly reversed by administration of anti-IFNAR1." (PMID 35847556, 2022). "However, the splenomegaly in Ifnar1-/- mice subsisted in eosinophil depleted mice and percentages of CD8+ T cells in spleens of PbA-infected and eosinophil depleted Ifnar1-/- mice remained similar to infected Ifnar1-/- mice that received isotype control antibodies." (PMID 34659202, 2021). "Along this line, the difference in viral RNA levels was much smaller between the spleens of Ifnar1−/− and MAR1-5A3-treated mice, which might explain the development of splenomegaly in these animals." (PMID 37112795, 2023). "The Ifnar1-/- mice presented a strong splenomegaly, even in the absence of Plasmodium infection." (PMID 34659202, 2021). "However, crossing ABIN1[D485N] mice to IFNAR1-knockout mice that do not express the α-subunit of the type 1 IFNR did not prevent splenomegaly, the appearance of high serum levels of autoantibodies and other Igs, or liver inflammation and only reduced kidney inflammation modestly." (PMID 27807192, 2016).
colorectal cancer (9 papers, 2019 to 2025). A primary or metastatic malignant neoplasm that affects the colon or rectum. "We determined that the expression level of PDCD1 is positively correlated with the levels of IFNB1 and IFNAR1 in myeloid cells in human colorectal cancer." (PMID 38995014, 2024). "We report here that the PDCD1 transcription level exhibits a positive correlation with the IFNB1 and IFNAR1 level in myeloid cells in human colorectal cancer patients." (PMID 38995014, 2024). "We report that the expression level of PDCD1, the gene that encodes the PD-1 protein, is positively correlated with the levels of IFNB1 and IFNAR1 in myeloid cells in human colorectal cancer." (PMID 38995014, 2024). "In colorectal cancer, IFNAR1 was shown to be actively degraded in the tumor tissue by phosphorylation-dependent ubiquitination, which was supported by VEGF." (PMID 35833131, 2022). "(D), (E) FCM determination demonstrated that colorectal cancer patients with positive VPS9D1-AS1 expression had lower levels of IFNAR1 in CD4+ and higher levels of PD1 in CD8+ T cells in peripheral blood than these patients with negative VPS9D1-AS1 expression." (PMID 36458816, 2022). "Our recent work demonstrated that IFNAR1 was downregulated on all types of cells in the tumor microenvironment of colorectal cancers leading to inactivation of the IFN1 pathway and generation of immune-privileged niches." (PMID 33741967, 2021). "IFNAR1 expression level is significantly lower in human colorectal carcinoma tissue than in normal colon tissue." (PMID 31228946, 2019). "Human colorectal carcinoma may use down-regulation of IFNAR1 on CTLs to suppress CTL effector function to evade host cancer immunosurveillance." (PMID 31228946, 2019). "We report here that the intrinsic IFN-I signaling pathway is essential for CTL effector function in tumor suppression and human colorectal carcinoma may use down-regulation of the IFNAR1 on CTLs to impair CTL effector function to evade host cancer immunosurveillance." (PMID 31228946, 2019).
glioma (9 papers, 2015 to 2024). A benign or malignant brain and spinal cord tumor that arises from glial cells (astrocytes, oligodendrocytes, ependymal cells). "To further investigate the function of IFNAR1 in mouse glioma models, we generated glioma sublines deficient for Ifnar1 using CRISPR/Cas9-mediated knockout." (PMID 36571986, 2023). "Furthermore, two type I IFN single nucleotide polymorphisms have been associated with poorer survival in glioma patients and TCGA analysis revealed an association with inferior survival in patients with tumors with high IFNAR1 RNA expression." (PMID 36571986, 2023). "In the current study, IFNAR1 depletion resulted in a phenotype in vivo only in the glioma model that exhibited constitutive type 1 IFN signaling." (PMID 36571986, 2023). "CT-2A, GL-261, SMA-497, SMA-540 and SMA-560 murine glioma cells expressed IFN type I receptors IFNAR1 and IFNAR2 and were responsive to exogenous IFN stimulation." (PMID 36571986, 2023). "Glioma-induced Ifnar1-/- mice show decreased infiltration of CD8+ T cells and reduced potency in their cytotoxic functions." (PMID 37304294, 2023). "The Gl261, CT2A, and SMA-560 glioma cell lines uniformly express IFNAR1 and IFNAR2." (PMID 37304294, 2023). "In the SMA-560 model, the host may provide growth-promoting cues to IFNAR1-deficient glioma cells that are not available in vitro." (PMID 36571986, 2023). "However, the silencing of IFN-α/β receptors 1 or 2 (IFNAR1 or IFNAR2), which constitute a loop to IFN-α signaling, causes a reduction in PD-L1 and MHC class I/II expression in glioma cells, as well as an enhanced susceptibility to immune cell lysis of NK cells." (PMID 29721184, 2018). "All five mouse glioma cell lines uniformly expressed mRNA for both type I IFN receptors, Ifnar1 and Ifnar2." (PMID 36571986, 2023). "To understand the role of autocrine or paracrine type I IFN signaling in murine glioma models in vitro and in vivo, we utilized CRISPR/Cas9 to disrupt the Ifnar1 gene." (PMID 36571986, 2023). "We detected IFNAR1 and IFNAR2 mRNA and protein and mRNA of ligands IFN-α and IFN-β in all human glioma cell lines tested." (PMID 36571986, 2023). "We also showed that IFN receptor (e.g., IFNAR1) and ISGs (e.g., EIF2AK2 and MAVS) were prognostic and editing-regulated in glioma." (PMID 35406793, 2022). "Moreover, SNPs affecting interferon (alpha, beta and omega) receptor 1 (IFNAR1) have been associated with an increased risk for the development of CRC amongst 2085 individuals, as well as with significantly reduced overall survival in a cohort of 304 glioma patients." (PMID 26300886, 2015). "•IFNAR1 knockout decreased proliferation in vitro in SMA-560 and GL-261 glioma cells." (PMID 36571986, 2023).